COL1A1 (collagen type I alpha 1 chain)
Diseases named in the same sentence as COL1A1 in open-access papers (continued):
Sharing a sentence is not in itself a finding about the gene and the disease.
Hyperglycemia (8 papers, 2013 to 2025). An increased concentration of glucose in the blood. "Accordingly, hyperglycemia-induced expressions of COL-1A1 and TGF-β were significantly suppressed by PHL in diabetic mice." (PMID 31076562, 2019). "Indeed, chronic hyperglycaemia is known to up-regulate various pro-fibrotic genes in the diabetic heart as a whole, including Col1a1, Postn, Timp-2 and Ccn2." (PMID 34074290, 2021). "Additionally, hyperglycemia could activate the YAP/TAZ signaling pathway in cancer-associated fibroblasts to upregulate expression of fibronectin, fibroblast activation protein, COL1A1 and COL11A1, to enhance EMT and chemoresistance of PC." (PMID 38581008, 2024). "During hyperglycemia, a combined treatment also reduced COL1A1 expression, while single treatments did not induce any desired effects." (PMID 37313172, 2023).
Hypertension (8 papers, 2020 to 2025). The presence of chronic increased pressure in the systemic arterial system. "Additionally, this study found that fibrotic markers Col1a1, Col3a1, and Fn1, as well as renal interstitial fibrosis, were significantly reduced following macrophage depletion in existing hypertension." (PMID 41175639, 2025). "Col1a1 expressed by PVMs supports the concept that PVMs are involved in hypertension." (PMID 36514189, 2023). "Unexpectedly, the HFC diet induced COL1A1 similarly across strains, suggesting that hypertension did not further increase ECM synthesis." (PMID 33315911, 2020). "In our present study, DF treatment and exercise significantly reduced the expression of fibrotic protein markers such as uPA, CTGF, COL1A1, and COL3A1, as well as hypertrophy markers such as NFATC3, GATA4, BNP, and ANP, which indicates that it could attenuate hypertension-mediated myocardial injury." (PMID 35890118, 2022).
leiomyoma (8 papers, 2008 to 2026). A well-circumscribed benign smooth muscle neoplasm characterized by the presence of spindle cells with cigar-shaped nuclei, interlacing fascicles, and a whorled pattern. "To explore the effect of UCHL1 silencing and inhibition in leiomyoma and myometrial cells, we detected the expression of COL1A1 and COL3A1 mRNA using quantitative real-time PCR." (PMID 36830563, 2023). "To explore the effects of UCHL1 knockdown and inhibition in leiomyoma and myometrial cells, we determined the mRNA expressions of COL1A1 and COL3A1." (PMID 36830563, 2023). "In addition, the expression of MIAT correlated with the MED12 mutation status of the leiomyomas, and knock down of MIAT in leiomyoma smooth muscle cells’ spheroids blocked the effects of TGF-β3 on the induction of COL1A1 and COL3A1 expression." (PMID 38279317, 2024). "As for the surgical approach, the risk of inadvertent dissemination of occult malignancies of presumed benign tissue must be considered, as COL1A1–PDGFB fusion uterine sarcomas could be judged as benign leiomyoma on imaging." (PMID 36994196, 2023). "Furthermore, RSV reduced leiomyoma cell viability, and decreased the mRNA levels of fibronectin and the protein expression of collagen type 1 (COL1A1) and α-SMA (ECM protein marker), as well as reducing the levels of β-catenin protein." (PMID 31013842, 2019). "COL1A1 and COL3A1 expression levels were downregulated after inhibition of UCHL1 in human leiomyoma cells." (PMID 36830563, 2023). "Taken together, ATRA exposure reduced COL1A1 and COL4A1 mRNA expression in leiomyoma cells, approaching expression patterns comparable to myometrial cells." (PMID 18248652, 2008). "The mRNA expression was increased for collagen genes COL1A1 (2·72 ± 0·55-fold; P < 0·05) and COL4A1 (2·95 ± 0·37-fold; P < 0·05) in leiomyoma cells as compared to myometrial cells prior to treatment." (PMID 18248652, 2008). "In a pathological setting, leiomyoma, LMS, HGESS, and undifferentiated uterine sarcoma should be considered as the main differential diagnosis of COL1A1–PDGFB fusion uterine sarcomas, and NTRK fusion uterine sarcoma should be the most challenging one to be differentiated." (PMID 36994196, 2023). "The expression of COL1A1 and COL3A1 significantly decreased in leiomyoma cells." (PMID 36830563, 2023). "The involvement of many proteins such as FN1, COL1A1, BMP7, CCND1, EZH2, HMGA2, AhR, and E2F1 shown in the protein–protein interaction networks are well known in leiomyoma pathogenesis; others, such as SOX2, REN, PPARG, ABCB1, and NR3C1 are novel and require further investigation." (PMID 36835153, 2023). "In agreement with the results of these studies, our results showed that 100 μM RSV significantly decreased the protein expression of COL1A1, α-SMA, and β-catenin, as well as the mRNA level of FN1 (fibronectin) in primary human leiomyoma cells compared to controls in vitro." (PMID 31013842, 2019). "A fourfold down-regulation (0·61 ± 0·14-fold; P < 0·05) of COL1A1 gene template was observed in leiomyoma cells at concentration of 10−8m ATRA, with no further significant fold change at higher concentrations." (PMID 18248652, 2008). "Fib-EXO increased the expression of vimentin, EZH2, DNMT1, TGF-β3, and c-MYC, and phosphorylated p65 protein, reduced COL1A1 and COL3A1 expression, and decreased miR-133a, miR-29, and miR-200c while increasing miR-21 in cultured myometrial smooth muscle cells, mirroring changes observed in fibroids." (PMID 42008339, 2026). "Additionally, APC protein levels were decreased in leiomyomas, while levels of non-phosphorylated β-Catenin at Ser45 (active form), total β-Catenin, and COL1A1 were increased." (PMID 39519092, 2024). "Additionally, we observed a correlation between elevated COL1A1 expression and decreased LINCMD1 levels in leiomyomas, which could be reversed by correcting miR-135b levels." (PMID 39519092, 2024).
Marfan syndrome (8 papers, 2013 to 2025). A disorder of the connective tissue. "Altogether, only 17 genes were primarily identified in relation to cervical insufficiency, with six being syndromic, i.e. COL1A1 and COL3A1 causing EDS; FBN1 causing Marfan syndrome; ZMPSTE24 and LMNA causing restrictive dermopathy; and MATR3 causing myopathy." (PMID 32214361, 2020). "Moreover, as supported by the literature, several have been associated with hernia formation, Ehlers–Danlos syndrome, and Marfan’s syndrome (e.g., COL1A1, COL3A1, COL5A1, FBN1, and TIMP1)." (PMID 22648066, 2013).
skin aging (8 papers, 2015 to 2025). The gradual irreversible changes in structure of skin that occur as a result of the passage of time.. "The degradation of COL1A1 is a hallmark feature of skin aging, leading to decreased skin firmness and the formation of wrinkles and fine lines." (PMID 38465340, 2024). "In skin aging, it has been shown that IL-8 and IL-6 are clearly linked to MMPs modulation and COL1A1 gene and protein expression." (PMID 31001530, 2019). "The results on COL1A1 expression levels provide additional evidence to support the use of collagen peptides as a food supplement with beneficial effects on the skin, mainly due to the fact that it compensates for the loss of collagen, which is one of the causes of skin aging." (PMID 38751975, 2024). "The reduction in telomere length, a marker of aging, can be quantified by the diminished expression of TERT, and a decline in COL1A1 expression is correlated with skin aging." (PMID 39296334, 2024). "In a previous study, it was shown that dietary suberic acid protects hairless mice against UVB-mediated skin aging by increasing collagen content and collagen synthesis genes, such as collagen type I alpha 1 chain (COL1A1)." (PMID 36552724, 2022). "The molecular function of suberic acid remains unknown; however, it can protect hairless mice from ultraviolet light-mediated skin aging by increasing collagen content and collagen synthesis genes (COL1A1)." (PMID 37833943, 2023).
Insulin resistance (7 papers, 2015 to 2025). Increased resistance towards insulin, that is, diminished effectiveness of insulin in reducing blood glucose levels. "In fact, curcumin, polydatin, quercetin, and hesperetin can increase the levels of the pro-osteogenic markers COL1A1 and ALP and inhibit the catalytic activity of the enzymes caspase 1 and DPPIV, which play a fundamental role in the development of the insulin resistance condition in T2DM." (PMID 39062550, 2024). "The dysregulation of extracellular matrix proteins like COL1A1 and CTSD suggests alterations in tissue remodeling processes and may contribute to the development of metabolic complications, such as insulin resistance and cardiovascular diseases." (PMID 38732002, 2024).
liver cirrhosis (7 papers, 2021 to 2025). "The qPCR results demonstrated that all three components significantly reduced the mRNA levels of COL1A1 in TGF-β1-induced liver cirrhosis model." (PMID 38429802, 2024). "Although the ROC values for CXCL8 (AUC = 0.583) and COL1A1 (AUC = 0.5833) were below 0.6, this does not negate their diagnostic efficacy for liver cirrhosis." (PMID 41223189, 2025). "Also, the expressions of α-SMA and COL1A1 co-cultured with serum exosomes of liver cirrhosis patients were significantly higher compared to that of healthy adults (P < 0.05)." (PMID 34843038, 2022). "Compared with the common homozygous genotype, the effect of the GC or GC + CC variant genotypes for COL1A1 rs2269336 and the TC or TC + CC genotypes for BRAF rs76603725 was more evident in males, liver cirrhosis, tumor number ≥3, tumor maximum diameter ≥5 cm, and tumor in two lobes." (PMID 34007838, 2021). "The roles of COL1A1 and COL1A2 in liver cirrhosis were confirmed in the stained samples, and higher expression levels were found in the advanced stages of liver cirrhosis." (PMID 41223189, 2025). "We co-cultured the serum exosomes from healthy adults and liver cirrhosis patients with HSC for 24 h respectively, and analyzed the expression of miR-574-5p, COL1A1, and α-SMA." (PMID 34843038, 2022).
lymph node metastasis (7 papers, 2016 to 2024). "Our study found that upregulation of COL1A1 expression is significantly associated with lymph node metastasis of OC and can affect the immune microenvironment." (PMID 39845977, 2024). "Here, we provide evidence that supports COL1A1 as a diagnostic marker that indicates the presence of lymph node metastasis." (PMID 33062455, 2020). "Nevertheless, little is known about the functional role of COL1A1 in elastography feature differences and axillary lymph node metastasis (LNM) of breast lesions." (PMID 36131254, 2022). "In lung squamous cell carcinoma, COL1A1 overexpression in the microenvironment is highly correlated with lymph node metastasis." (PMID 34503278, 2021). "Studies investigating the mechanistic link between fibrosis and lymph node metastasis will help in further validating COL1A1’s role in cancer progression." (PMID 33062455, 2020). "This study aimed to explore whether collagen fiber features and collagen type I alpha 1 (COL1A1) are related to the stiffness of breast lesions and whether COL1A1 can predict axillary lymph node metastasis (LNM)." (PMID 36131254, 2022). "COL1A1 expression can be used to predict lymph node metastasis." (PMID 36131254, 2022). "The expression of COL1A1 may be helpful in diagnosing benign and malignant breast lesions and predicting axillary lymph node metastasis." (PMID 36131254, 2022). "Finally, evaluation of clinical biopsy samples suggests that overexpression of COL1A1 in the LSCC microenvironment highly correlates with lymph node metastasis." (PMID 33062455, 2020). "The results indicated a significant overexpression of COL1A1 in OC samples, with the lymph node metastasis-positive (LNM+) group exhibiting notably higher levels of COL1A1 expression compared to the lymph node metastasis-negative (LNM-) group." (PMID 39845977, 2024). "The reason why COL1A1 expression did not correlate with depth of invasion and lymph node metastasis in this study needs to be further explored." (PMID 27894325, 2016).
metastatic disease (7 papers, 2015 to 2024). "Interestingly, tumor cells harboring KRAS G12V upregulate several genes associated with more aggressive or metastatic tumors, including COL1A1, VIM and MUC5B 42–44." (PMID 35995947, 2022). "Moreover, MT staining and immunohistochemical staining of COL1A1 demonstrated newly synthesized ECM around and inside the A549-KO metastatic tumors." (PMID 37626065, 2023).
non-small cell lung carcinoma (7 papers, 2017 to 2025). A group of at least three distinct histological types of lung cancer, including non-small cell squamous cell carcinoma, adenocarcinoma, and large cell carcinoma. "While mutations in the COL1A1 gene may lead to other non-small cell lung cancers (e.g., large cell carcinomas and adenocarcinomas), it was nearly 2x as likely to mutated in squamous cell carcinomas." (PMID 33062455, 2020). "Moreover, miR-29b-3p reverses cisplatin resistance in non-small cell lung cancer cells by targeting COL1A1, highlighting the critical role of COL1A1 in metastasis and drug resistance." (PMID 40851082, 2025). "Evidence also showed that hypoxia augmented the transcription and deposition of COL1A1 by TGF- β pathway, and COL1A1 was identified as a hypoxia marker in the non-small cell lung carcinoma." (PMID 31552163, 2019). "Residual chemoresistant, slow-cycling cancer cells (SCCs) regulate CAFs through multiple pathways, including COL1A1-mediated signaling pathways, to establish a growth-promoting TME for SCCs, restoring the proliferative capacity of quiescent non-small cell lung cancer cells." (PMID 38280909, 2024). "Type I collagen (COL1A1 and COL1A2) was correlated with the resembling of TAMs in non-small cell lung carcinoma (NSCLC) while it was not correlated with the paucity of T-cell accumulation in pancreatic ductal adenocarcinoma (PDAC), which were consistent with our results." (PMID 33543230, 2021).
pancreatic ductal adenocarcinoma (7 papers, 2019 to 2025). An infiltrating adenocarcinoma that arises from the epithelial cells of the pancreas. "A novel in vivo approach using mannose-modified mRNA lipid nanoparticles to target CD206 on M2 reprogrammed them into FAP-CAR-M, yielding decreases in activated cancer-associated fibroblast markers, collagen volume, and Col1a1 in a pancreatic ductal adenocarcinoma model." (PMID 41357209, 2025). "Circ-0007334 regulates MMP-7 and collagen type I alpha 1 chain (COL1A1) by competitively adsorbing miR-144-3p and miR-577 to enhance the expression and functions of MMP-7 and COL1A1 in pancreatic ductal adenocarcinoma (PDAC)." (PMID 31973726, 2020).
arthrochalasia EDS (6 papers, 2021 to 2025). "Arthrochalasia EDS (aEDS), caused by COL1A1 or COL1A2 genetic mutations, has symptoms of extreme joint laxity, recurrent dislocations, and congenital hip dysplasia, often resulting in proprioceptive imprecision that impairs coordination and elevates injury risk." (PMID 41245867, 2025). "In addition, in a study of 12 patients with Arthrochalasia Ehlers-Danlos syndrome (aEDS), the majority (10/12) of patients had total or partial loss of COL1A1 or COL1A2 exon 6, five of whom underwent hip joint surgery." (PMID 39156961, 2024).
diabetic kidney disease (6 papers, 2020 to 2025). Progressive kidney disorder caused by vascular damage to the glomerular capillaries, in patients with diabetes mellitus. "Previous research has demonstrated that the miR-29 family is downregulated in diabetic nephropathy and diabetic cardiomyopathy, where it suppresses collagen gene expression (including COL1A1, COL4A1, and COL6A2) and is closely linked to TGF-β signaling." (PMID 41583295, 2025). "For the first layer of predictive model, a biomarker panel consisting of 22 predictive marker candidates was established to distinguish healthy controls from patients with T2DM or diabetic kidney disease, including malonic acid, pep_1047.36_COL1A1 and so on." (PMID 37351171, 2023). "Based on the results of transcriptomics, the pathogenesis of diabetic kidney disease may involve 11 candidate differential genes: Egr1, Foxo3, Pik3r3, Fgf1, Sost, Wnt10a, Tgif2, Akt2, Mep1b, Col1a1, Apoe." (PMID 36249745, 2022). "COL1A1, collagen type I alpha 1 chain, is related to diabetic kidney disease." (PMID 32993645, 2020).
hearing loss (6 papers, 2011 to 2024). "In contrast, all relatives from three unrelated families affected by the same underlying COL1A1 mutation (c.769G > A) were diagnosed with a hearing loss characterized by a conductive component (families Nos." (PMID 22206639, 2011). "Therefore, we identified a novel mutation locus in COL1A1 by genetic testing of OI patients and summarized the current status and prognosis of hearing loss studies in OI patients, with the aim of providing some help in the diagnosis and treatment of OI patients with hearing loss." (PMID 37678008, 2023). "Several collagen genes (COL1A1, COL1A2, COL2A1, COL4A3, COL4A4, COL4A5, COL11A1, and COL11A2) are associated with hereditary syndromic hearing loss." (PMID 33848312, 2021). "Participants in the COL1A1/1A2 group were more likely to be diagnosed with hearing loss later into childhood than participants in the non-COL1A1/1A2 group, but the difference was not significant (p = 0.13)." (PMID 39450342, 2024). "Site-specific mutations in COL1A1, GJC3, RRM2B, SALL4, and SALL1 cause otosclerosis ([MIM:120150]), delayed hearing sensitivity ([MIM:611925]), sensorineural deafness ([MIM: 604712]), hearing loss ([MIM:607343]) and ear dysplasia ([MIM:602218]), among other deafness-related disorders." (PMID 36803022, 2023).
oral cancer (6 papers, 2018 to 2024). "Oral cancer proliferation and invasion can be suppressed by miR-133a-3p over-expression and collagen type I alpha 1 chain gene (COL1A1) direct targeting." (PMID 29482431, 2018). "In line with our findings, previous studies on oral cancer cells have also reported the inhibitory effects of CTX on crucial modulators associated with cell migration and invasion, including MMP-2, MMP-9, and COL1A1." (PMID 39114354, 2024). "Furthermore, using oral cancer data from The Cancer Genome Atlas (TCGA), we observed that MEG3 was positively correlated with α-SMA and COL1A1." (PMID 35890132, 2022).